ERFE (erythroferrone)
Description:
Iron-regulatory hormone that acts as an erythroid regulator after hemorrhage: produced by erythroblasts following blood loss and mediates suppression of hepcidin (HAMP) expression in the liver, thereby promoting increased iron absorption and mobilization from stores. Promotes lipid uptake into adipocytes and hepatocytes via transcriptional up-regulation of genes involved in fatty acid uptake (By similarity). Inhibits apoptosis and inflammatory response in cardiomyocytes via promotion of sphingosine-1-phosphate (S1P) and cAMP-dependent activation of AKT signaling (By similarity). Inhibits autophagy induced by nutrient deficiency in hepatocytes via promoting the phosphorylation of IRS1, AKT, and MTOR, and thereby subsequent activation of the AKT-MTOR signaling pathway (By similarity). Negatively regulates the differentiation of osteoblasts, potentially via sequestering BMP2, and thereby inhibits the activation of SMAD signaling (By similarity). The reduction in BMP2 signaling in osteoblasts also results in an increase in expression of the osteoclastogenesis-promoting factors TNFSF11/RANKL and SOST, thereby indirectly promotes bone resorption (By similarity).
Synonyms: C1QTNF15; CTRP15; FAM132B; FLJ37034
Tractability: Antibody: UniProt places it where antibodies can reach, with medium confidence; UniProt predicts a signal peptide or a membrane-spanning region; its Gene Ontology location is reachable by antibodies, with medium confidence.
Gene: Protein-coding gene on chromosome 2 (238,158,970 to 238,168,900, forward strand). Ensembl gene ENSG00000178752.
Subcellular location: Secreted
Gene Ontology:
Molecular function: molecular sequestering activity; hormone activity; identical protein binding
Biological process: negative regulation of BMP signaling pathway; intracellular iron ion homeostasis; negative regulation of apoptotic process; negative regulation of autophagy; negative regulation of gluconeogenesis; negative regulation of osteoblast differentiation; negative regulation of osteoclast differentiation; positive regulation of D-glucose import; positive regulation of insulin receptor signaling pathway; positive regulation of phosphatidylinositol 3-kinase/protein kinase B signal transduction; regulation of signal transduction; signal transduction
Cellular component: extracellular region
Genetic constraint (gnomAD): Loss-of-function variants: 28 observed, 22.46 expected, observed/expected ratio (o/e) 1.25, 90% interval 0.92 to 1.7. The synonymous counts are far from expectation, so gnomAD's model fits this gene poorly and the ratio says little. Missense variants: 447 observed, 351.49 expected, observed/expected ratio (o/e) 1.27, 90% interval 1.18 to 1.38. Synonymous variants: 206 observed, 163.27 expected, observed/expected ratio (o/e) 1.26, 90% interval 1.12 to 1.42.
Homologues: Orthologues: chimpanzee ERFE (99% identical), pig ERFE (79% identical), dog ERFE (73% identical), mouse Erfe (71% identical), rat Erfe (71% identical), guinea pig ERFE (70% identical), rabbit ERFE (66% identical), tropical clawed frog erfe (28% identical). Paralogues in human: C1QTNF12 (34% identical).
Diseases named in the same sentence as ERFE in open-access papers:
ERFE is named in the same sentence as 50 diseases in open-access papers, as found by Europe PMC text mining. Sharing a sentence is not in itself a finding about the gene and the disease. The quoted sentences say what the papers report.
anaemia (12 papers, 2017 to 2025). "Supporting this hypothesis, constitutive ERFE-knockout mice with CKD (EKO-CKD) treated with the HIF prolyl hydroxylase inhibitor vadadustat — an agent used to treat CKD-associated anemia — displayed significantly lower BUN and serum creatinine levels compared with vehicle-treated EKO-CKD mice." (PMID 40773297, 2025). "They underscore the central role of splenomegaly in VL‐related anaemia and suggest potential contributions from other factors affecting iron metabolism, such as erythropoietin and erythroferrone." (PMID 40637365, 2025). "In the current study, we employed a common preclinical mouse model of CKD to verify the concept that the endogenous erythroid hormone ERFE can be used therapeutically to ameliorate anemia." (PMID 40773297, 2025). "In response to malaria induced anemia, erythropoietin levels are found to be higher in malaria patients, which in turn promotes erythrocyte formation and stimulates erythroferrone (negative regulator of hepcidin) production." (PMID 39492784, 2024). "Within our case series (28 CDA II patients), approximately 36% of them exhibit severe iron overload despite mild degree of anemia and slightly increased levels of ERFE (the only erythroid regulator of hepcidin suppression)." (PMID 35163229, 2022). "ERFE has a role in the recovery from anaemia of inflammation, as demonstrated in a mouse model of ACD induced by injection of heat-killed Brucella abortus; in this model, through the suppression of hepcidin, ERFE contributes to the recovery from ACD." (PMID 28191453, 2017). "ERFE, a hormone produced by erythroblasts in the bone marrow, plays a crucial role in regulating iron metabolism, particularly during increased RBC production, such as in anaemia or after blood loss." (PMID 39940645, 2025). "Our data might explain CDA II cases showing marked iron overload despite mild or slight degree of anemia where the role of ERFE seems to be secondary." (PMID 35163229, 2022). "Although not tested in the present study, ERFE's involvement in iron regulation may mean that it has direct relevance to HF patients with anaemia, as iron deficiency is estimated to be present in up to 50% of chronic heart failure patients." (PMID 38259307, 2023). "ERFE is a glycoprotein hormone, which along another the erythropoietic regulator, is secreted by splenocytes and erythroblasts in response to ineffective erythropoiesis, anemia, hemorrhage, and EPO stimulation leading to the suppression of hepcidin production in hepatocytes." (PMID 36620219, 2022). "It highlights the role of key regulatory factors such as hepcidin, erythroferrone (ERFE), and growth differentiation factor 15 (GDF-15) in anaemia and erythropoiesis." (PMID 39940645, 2025). "Recent evidence show that erythroferrone (ERFE), a hepcidin suppressors, are both related to TIBC and haemoglobin, which suggested haematopoietic regulation, which links both anaemia and iron metabolism, needs to be taken into account." (PMID 31914941, 2020). "A mouse model study showed that animals lacking the ERFE gene (Erfe−/−) developed anaemia; however, this phenomenon only affected the period of intensive growth." (PMID 34827208, 2021).
iron overload (6 papers, 2019 to 2024). "Our data also demonstrate the effect of RAP-011 treatment in reducing the expression of erythroferrone in vitro, thus suggesting a possible beneficial role of the use of sotatercept in the management of iron overload in patients with CDA II." (PMID 32759740, 2020). "Patients treated with mitapivat showed decreases in both sTfR and erythroferrone, increases in hepcidin, and improvements in LIC from baseline, with improvements in LIC particularly marked in the subgroup of patients with iron overload at baseline." (PMID 38330179, 2024). "Moreover, erythroferrone (ERFE), the main erythroid regulator of hepcidin, is one of the key players of iron overload in thalassemia syndromes." (PMID 34575839, 2021).
Insulin resistance (5 papers, 2013 to 2023). Increased resistance towards insulin, that is, diminished effectiveness of insulin in reducing blood glucose levels. "MN, also referred to as erythroferrone (ERFE) or C1q/TNF‐related protein isoform 15 (CTRP15), is a pro‐inflammatory myokine and reported to be associated with insulin resistance." (PMID 36457269, 2022).
iron deficiency (3 papers, 2017 to 2023). "While the genes encoding erythroferrone and Gdf15 were upregulated in the bone marrow and spleen in most of the models examined, the highest levels were seen with iron deficiency." (PMID 28135344, 2017). "Results presented in this study demonstrate that iron overload or iron deficiency did not affect ERFE protein induction in the spleen." (PMID 30958854, 2019). "We also show that the synthesis of ERFE protein in the spleen of EPO-treated mice is not affected by iron pretreatment, and that iron deficiency posttranscriptionally downregulates TFR2 protein content in the spleen of erythropoietin-treated mice." (PMID 30958854, 2019).
thalassemia (3 papers, 2019 to 2025). An inherited blood disorder characterized by a decreased synthesis of one of the polypeptide chains that form hemoglobin. "The therapeutic potential of targeting ERFE has been demonstrated through the development of anti-ERFE antibodies that prevent hepcidin suppression and ameliorate murine thalassemia by specifically targeting the N-terminal domain of erythroferrone (ERFE)." (PMID 41446860, 2025). "In thalassemia, ineffective erythropoiesis induces the release of factors including GDF15, twisted gastrulation protein homolog 1 (TWSG1), hypoxia-inducible factor (HIF), and ERFE, which can all inhibit hepcidin release." (PMID 30834265, 2019).
myelodysplastic syndrome (2 papers, 2023 to 2025). A clonal hematopoietic disorder characterized by dysplasia and ineffective hematopoiesis in one or more of the hematopoietic cell lines. "We previously found that ERFE was upregulated in erythroid progenitors in myelodysplastic syndromes and strongly predicted overall survival." (PMID 36675239, 2023).
adrenocortical carcinoma (1 paper, 2023). "In certain tumors such as breast cancer and adrenocortical carcinoma, ERFE overexpression has been associated with the presence of oncogenic mutations and a higher tumor mutational burden." (PMID 36675239, 2023). "Of note, the highest number of these genes (n = 6) was positively co-regulated with ERFE in adrenocortical cancer and mesothelioma, cancers where high ERFE expression showed the strongest association with inferior survival." (PMID 36675239, 2023). "Furthermore, ERFE mRNA overexpression in bulk tumor tissues was an independent factor in predicting inferior survival in 11 tumor types, especially in adrenocortical carcinoma, mesothelioma, and uveal melanoma." (PMID 36675239, 2023). "In addition, we observed that in certain tumors, such as adrenocortical carcinoma and mesothelioma, ERFE was positively co-expressed with the NCAPH and KIF23 genes, which facilitate the separation of chromosomes and cytokinesis during mitosis, thereby promoting tumor cell proliferation." (PMID 36675239, 2023). "Higher ERFE expression was related to all three types of survival (OS, DSS, and PFI) in adrenocortical cancer, mesothelioma, pancreatic, colon, kidney clear cell, and skin cutaneous melanoma cancers, and indicated poor outcome." (PMID 36675239, 2023).
breast carcinoma (1 paper, 2023).
colon cancers (1 paper, 2023). "Among them, ERFE overexpression indicated poor prognosis in adrenocortical, pancreatic, and colon cancers." (PMID 36675239, 2023).
glioma (1 paper, 2023). A benign or malignant brain and spinal cord tumor that arises from glial cells (astrocytes, oligodendrocytes, ependymal cells).
iron disorders (1 paper, 2023). "By identifying the active site and determining the structural requirements for both hepcidin inhibition and stimulation, our structure-function study of ERFE may help inform the design of new therapeutics targeting ERFE or BMPs for the treatment of iron disorders." (PMID 37866631, 2023).
melanoma (1 paper, 2023). A malignant, usually aggressive tumor composed of atypical, neoplastic melanocytes. "Indeed, our analysis revealed that ERFE overexpression was pronouncedly associated with the presence of metastases in prostate cancer and melanoma." (PMID 36675239, 2023).
Myelodysplasia (1 paper, 2024). Clonal hematopoietic stem cell disorders characterized by dysplasia (ineffective production) in one or more hematopoietic cell lineages, leading to anemia and cytopenia. "Whereas its role in iron homeostasis as a physiological erythropoietic regulator of iron metabolism is rather well-established, the involvement of ERFE in regulation of iron metabolism in MDS and also its contribution to the pathogenesis of myelodysplasia is de facto still unknown." (PMID 38835379, 2024).
testicular germ cell tumor (1 paper, 2023). A germ cell tumor arising from the testis. "Overall, one could envision that in thyroid cancer, testicular germ cell tumors and uveal melanoma ERFE upregulation contribute to NOTCH signaling and its effects on tumor progression, which needs to be determined in functional studies." (PMID 36675239, 2023). "Our study showed a strong positive correlation between ERFE and HES6 expression in thyroid cancer, uveal melanoma, and testicular germ cell tumors." (PMID 36675239, 2023).
thyroid cancer (1 paper, 2023). "Our study additionally identified that ERFE overexpression might be related to activated NOTCH-related signaling pathway, which is proven to be significantly involved in the tumorigenesis and tumor invasion in certain cancers including thyroid cancer and uveal melanoma." (PMID 36675239, 2023).
uveal melanoma (1 paper, 2023). A melanoma derived from melanocytes of the uveal tract. "Interestingly, in our study HES6 was strongly co-expressed with ERFE in uveal melanoma, which was associated with distant metastasis." (PMID 36675239, 2023).
cancer (6 papers, 2021 to 2025). A tumor composed of atypical neoplastic, often pleomorphic cells that invade other tissues. "ERFE (erythroferrone) is a secreted erythroid hormone that tunes iron homeostasis, in silico pan-cancer analyses indicate broad overexpression linked to poorer outcomes." (PMID 41411367, 2025). "Due to the strong association of the ERFE expression with prognosis in multiple types of cancer, we next sought to provide explanations for this observation via analysis of available mutational data." (PMID 36675239, 2023). "Finally, even though we found that the hormone ERFE is upregulated in human pre-cachectic and cachectic muscle biopsies, longitudinal studies in cancer patients are required to determine causality and the identification of ERFE as potential prognostic marker." (PMID 38052214, 2023). "The pathway enrichment analyses additionally demonstrated that in these five cancers, ERFE overexpression was associated with upregulated signaling pathways involved in the cell cycle, mitotic process, and DNA replication, which are tightly associated with genomic instability." (PMID 36675239, 2023). "In summary, we reported aberrant expression and prognostic significance of ERFE at the pan-cancer level." (PMID 36675239, 2023). "In this study, we carried out a comprehensive in silico analysis for the ERFE gene based on publicly available Omics data to further investigate the potential molecular mechanisms by which ERFE contributes to tumorigenesis and prognosis in cancer." (PMID 36675239, 2023). "Our analysis shows that the ERFE mRNA is significantly overexpressed in 22 tumors and affects the prognosis in 11 cancer types." (PMID 36675239, 2023). "We found indeed that the BMP inhibitor ERFE is more expressed in models of cancer cachexia and in muscles of pre-cachectic and cachectic cancer patients." (PMID 38052214, 2023). "Although ERFE expression was limited to several healthy tissues, we found that ERFE was widely expressed in cancer cell lines." (PMID 36675239, 2023). "Conclusively, ERFE is aberrantly expressed in pan-cancer and can potentially function as a prognostic biomarker based on its putative functions during tumorigenesis and tumor development." (PMID 36675239, 2023). "Through detailed analyses of mRNA expression and its associations with prognosis, mutational burden, immune infiltrates, and the enrichment of signaling pathways, the role of the ERFE gene in 33 types of cancer was evaluated." (PMID 36675239, 2023). "To understand the potential molecular interactions and identify cues for further functional investigation and the prognostic impact of ERFE in other malignancies, we performed a pan-cancer in silico analysis utilizing the Cancer Genome Atlas datasets." (PMID 36675239, 2023). "In n = 5 cancer entities, ERFE was significantly downregulated in tumor tissues as compared to the matched healthy tissues." (PMID 36675239, 2023). "Although cancer-related functions of some CTRPs have been clarified, the role of ERFE during tumorigenesis remains unknown." (PMID 36675239, 2023). "Therefore, our study utilized the TCGA dataset to comprehensively analyze the functions of ERFE (CTRP15) gene expression in cancer." (PMID 36675239, 2023). "Despite multiple reports about the involvement of CTRPs in cancer, the role of ERFE in cancer progression is largely unknown." (PMID 36675239, 2023). "The expression of ERFE is co-regulated with the factors and pathways involved in cancer progression and metastasis, including activated pathways of the cell cycle, extracellular matrix/tumor microenvironment, G protein-coupled receptor, NOTCH, WNT, and PI3 kinase-AKT." (PMID 36675239, 2023). "Next, we assessed whether deregulated expression of ERFE is of prognostic significance in pan-cancer." (PMID 36675239, 2023). "Altogether, these data suggest that ERFE might play a role in tumorigenesis and potentially affect prognosis in patients with cancers." (PMID 36675239, 2023).
cancer (continued). "Due to the recently discovered prognostic and functional role in iron homeostasis in myeloid neoplasia, in this study we focused on the somatic expression profiles and putative cancer-related functions of CTRP15 (also named as erythroferrone [ERFE] and myonectin)." (PMID 36675239, 2023). "Overall, high ERFE expression was related to inferior prognosis in most analyzed cancer entities." (PMID 36675239, 2023). "However, a comprehensive assessment of ERFE expression in cancerous tissues and its association with cancer has not been performed yet." (PMID 36675239, 2023). "Our results demonstrated that, in cancer cachexia, a state of systemic inflammation contributes to the upregulation of the BMP scavenger ERFE through STAT3 activation." (PMID 38052214, 2023). "Several iron-related genes, such as scavenger receptor class A member 5 (SCARA5), erythroferrone (ERFE), lipocalin 2, TfR2, SLC11A1, and cytochrome B reductase 1 (CYBRD1), were found to be dysregulated in different cancers, likely due to abnormal DNA methylation." (PMID 39595619, 2024). "Single cell RNA sequencing datasets available at “scTIME Portal” showed that the ERFE gene was not expressed in a broad range of immune cells (e.g., T cells, B cells, NK cells, macrophages, monocytes, neutrophils, etc.)in pan-cancer (data not shown)." (PMID 36675239, 2023). "It should be noted that our study does not exclude the possibility that ERFE is not a key factor in the progression of many cancers, but rather a molecule that is passively co-regulated with factors strongly involved in cancer progression." (PMID 36675239, 2023). "Nevertheless, the current lack of functional data does not diminish the value of ERFE as a potential prognostic biomarker in many types of cancer." (PMID 36675239, 2023). "In addition, ERFE was co-expressed with the genes involved in extracellular matrix (ECM) deposition and remodeling, including PXDN, COL4A1, and LOXL2 that are known to promote cancer invasion and metastasis." (PMID 36675239, 2023).